FLT3 (fms related receptor tyrosine kinase 3)
Diseases named in the same sentence as FLT3 in open-access papers (continued):
Sharing a sentence is not in itself a finding about the gene and the disease.
acute myeloid leukemia (continued). "Acute myeloid leukemia (AML) patients with FMS-like tyrosine kinase 3-internal tandem duplication (FLT3-ITD) have a high relapse rate and poor prognosis." (PMID 32565734, 2020). "Otherwise, fragment analysis should be performed along with next generation sequencing to ensure prompt initiation of FLT3 inhibitor therapy in acute myeloid leukemia." (PMID 31471587, 2020). "Internal tandem duplication in the juxtamembrane domain of FLT3 (FLT3/ITD) is frequent molecular aberration which is detected in approximately 30% of the patients with acute myeloid leukemia and normal diploid karyotype (AML-CN)." (PMID 32333156, 2020). "FLT3-internal tandem duplication occurs in 20–30% of acute myeloid leukemia and confers an adverse prognosis with its allelic ratio being a key risk stratifier." (PMID 31471587, 2020). "Fms-like tyrosine kinase-3, internal tandem duplication (FLT3-ITD) mutation, is a known predictor for worse outcome in patients with acute myeloblastic leukemia (AML)." (PMID 33112537, 2020). "FLT3-ITD and FLT3-TKD mutations were observed in approximately 20 and 10% of acute myeloid leukemia (AML) cases, respectively." (PMID 32722298, 2020). "In this work we investigated the molecular mechanisms that control CDC25A transcription and translation in acute myeloid leukemia cells that express the FLT3-ITD mutant tyrosine kinase receptor." (PMID 32024878, 2020). "Collectively, in this study, we explored that ATO reduced the leukemic burden in the major hematopoietic organs of mice and induced the autophagic degradation of the FLT3-ITD protein in FLT3-ITD acute myeloid leukemia cells." (PMID 32284743, 2020). "These include acute myeloid leukemia (AML), FLT3-ITD AML (with FLT3-ITD mutations), and higher risk-myelodysplastic syndromes or chronic myelomonocytic leukemia." (PMID 34691526, 2020). "Mutated receptor tyrosine kinases (MT-RTKs) such as internal tandem duplication of FMS-like tyrosine kinase 3 (FLT3 ITD) and a point mutation KIT D816V are driver mutations for acute myeloid leukemia (AML)." (PMID 32811837, 2020). "In an acute myeloid leukemia mouse model, mice with constitutively activating internal tandem duplication (ITDs) of FLT3 (FLT3-ITD) show enhanced myeloproliferation and progressive loss of HSC function." (PMID 32849521, 2020). "A previous study demonstrated that high WBC count is a prognostic factor in patients with acute myeloid leukemia with the genotypic combination ‘NPMc (+) with FLT3-ITD’38." (PMID 32606327, 2020). "FLT3‐ITD tyrosine kinase inhibitors (TKI) show limited clinical activity in acute myeloid leukemia (AML) due to emerging resistance." (PMID 31955503, 2020). "Specifically, the best inhibition ability of 1 was against the FMS-like tyrosine kinase 3 (FLT3) internal tandem duplication mutation of the gatekeeper residue F691 (FLT3-ITD, F691L) involved in acute myeloid leukemia, among others." (PMID 33218150, 2020). "Prior studies suggest 20 nM crenolanib is sufficient to inhibit FLT3 (type-III tyrosine kinase inhibitor) in acute myeloid leukemia." (PMID 32411595, 2020). "In lung cancer, PRMT5 activity increases FGFR3 expression by repressing miR-99, and in AML (acute myeloid leukemia) PRMT5 repression of miR-29b upregulates FLT3." (PMID 32743345, 2020). "For instance, in ~30% of acute myeloid leukemia (AML) cases, STAT5B is activated by mutated FLT3 (Fms-Like Tyrosine Kinase 3)." (PMID 31717342, 2019). "CCT241736 is a dual fms-like tyrosine kinase 3 (FLT3)/Aurora kinase inhibitor in development for the treatment of acute myeloid leukaemia." (PMID 30953752, 2019). "For example, FLT3, a critical receptor tyrosine kinase mutated in up to 35% of acute myeloid leukemia (AML) cases was found to be one of the three highest impact genes in all three AML datasets." (PMID 31479446, 2019). "Internal-tandem duplications (ITDs) in the FMS-like tyrosine kinase 3 (FLT3) gene are frequently identified genetic alterations in acute myeloid leukemia (AML)." (PMID 30947742, 2019).
acute myeloid leukemia (continued). "Recently, examination of the bone marrow and SS lesional tissue in a patient with concurrent acute myeloid leukemia (AML) with single nucleotide polymorphism array and next generation sequencing revealed FLT-3 gene mutations in infiltrating mature neutrophils and neoplastic progenitor cells." (PMID 30930894, 2019). "At present, we evaluate an Fc-optimized (amino acid substitutions S239D/I332E) FLT3 antibody termed 4G8-SDIEM (FLYSYN) in patients with acute myeloid leukemia (NCT02789254)." (PMID 31817795, 2019). "The most advanced of our compounds is an Fc-optimized mAb, which targets FMS-like tyrosine kinase 3 (FLT3) expressed on the cell surface of leukemic cells in the vast majority of patients with acute myeloid leukemia (AML)." (PMID 31817795, 2019). "We conclude that co-occurrence of WT1 mutation, NUP98-NSD1, and FLT3-ITD with an AR ≥0.4 as triple or double mutations still predicts dismal response to contemporary first- and second-line treatment for pediatric acute myeloid leukemia." (PMID 31467532, 2019). "Fms-like receptor tyrosine kinase 3 (FLT3) has been emerging as an attractive target for the treatment of acute myeloid leukemia (AML)." (PMID 31731727, 2019). "Mutations of FMS-like tyrosine kinase 3 (FLT3) are often observed in acute myeloid leukemia (AML)." (PMID 31500396, 2019). "Muations in the fms-related tyrosine kinase 3 (FLT3) gene are prevalent in newly diagnosed acute myeloid leukemia (AML) cases, affecting up to 39% patients." (PMID 30046393, 2018). "Internal tandem duplication (ITD) in Fms-like tyrosine kinase 3 (FLT3) is frequently observed in acute myeloid leukemia (AML)." (PMID 30344940, 2018). "In acute myeloid leukemia (AML), internal tandem duplications (ITDs) of FLT3 are frequent mutations associated with unfavorable prognosis." (PMID 30046393, 2018). "Ponatinib is also being tested in clinical trials to evaluate its activity in FLT3-ITD acute myelogenous leukemia, head and neck cancers, certain type of lung cancer, gastrointestinal stromal tumours and other malignancies." (PMID 30423915, 2018). "FMS-like Tyrosine Kinase 3 (FLT3) is a clinically validated target for acute myeloid leukemia (AML)." (PMID 29487300, 2018). "Acute myeloid leukemia (AML) has poor prognosis due to various mutations, e.g., in the FLT3 gene." (PMID 30420889, 2018). "Quizartinib, an inhibitor of class III receptor tyrosine kinases (RTKs), is currently in phase 3 development for the treatment of acute myeloid leukemia (AML) bearing internal tandem duplications in the FLT3 gene." (PMID 30081867, 2018). "Acute myeloid leukemia (AML) is frequently characterized by mutations of the receptor TK FLT3." (PMID 30423915, 2018). "Acute myeloid leukemia (AML) patients with FLT3/ITD mutations have a poor prognosis." (PMID 30250637, 2018). "FLT3 mutations are one of the most common findings in acute myeloid leukemia (AML)." (PMID 30514344, 2018). "We studied three FLT3 ITD acute myeloid leukemia (AML) patients who relapsed after allogeneic haematopoietic stem cell transplantation (alloHSCT) and received multikinase inhibitor (MKI) sorafenib as part of salvage therapy." (PMID 29304116, 2018). "FMS-like tyrosine kinase 3 (FLT3) is a type III RTK expressed in approximately 90% of acute myeloid leukaemia (AML) and plays a critical role in normal haematopoiesis." (PMID 29285262, 2017). "Acute myelogenous leukemia (AML) is often associated with activating mutations in the receptor tyrosine kinase, Flt3, including internal tandem duplications (ITDs) within the regulatory juxtamembrane region." (PMID 28727840, 2017). "Although the tools are largely compatible with amplicon library, bioinformatics challenges exist in some scenarios, such as the detection of FLT3 internal tandem duplication in acute myeloid leukaemia by amplicon sequencing." (PMID 28484262, 2017).
acute myeloid leukemia (continued). "Previously we demonstrated that overexpression of Hedgehog downstream mediators GLI1/2 confers an adverse prognosis to patients with acute myeloid leukemia (AML) and is correlated with a FLT3 mutated status." (PMID 28418873, 2017). "STAT5 is activated in acute myeloid leukemia (AML), in particular in the subtypes harboring the internal tandem duplication (ITD) mutations of the tyrosine kinase FLT3." (PMID 29100302, 2017). "As an example, we also identified the well-known FLT3 tandem repeat involved in acute myeloid leukemia." (PMID 29623188, 2017). "In alignment with our findings, sunitinib was active against acute myeloid leukemias (AML) possessing activating PDGFR, FLT-3, and c-kit mutations through inhibiting mTOR and reducing Mcl-1 levels." (PMID 29066973, 2017). "Fms-like tyrosine kinase (FLT3) is a frequently mutated oncogene in acute myeloid leukemia (AML)." (PMID 27458164, 2016). "In this report, we have studied the role of FYN in FLT3 signaling in respect to acute myeloid leukemia (AML)." (PMID 26848862, 2016). "Somatic internal tandem duplication (ITD) mutations are an important oncogenic driver in Acute Myeloid Leukemia (AML), where an ITD within the juxta-membrane domain of FLT3 confers poor prognosis." (PMID 27121965, 2016). "However, similar to NPM1 and FLT3 mutations in acute myeloid leukemia (AML), SRSF2 mutations seem to occur later in the development of myeloid neoplasms than TET2 mutations." (PMID 27029036, 2016). "In acute myeloid leukemia (AML), the Fms-like tyrosine kinase 3 (FLT3) is one of the most frequently mutated genes." (PMID 27346558, 2016). "A member of the PDGFR-family receptor tyrosine kinase (also called type III receptor tyrosine kinases), FLT3, has been shown to be deregulated in acute myeloid leukemia (AML) and in a small portion of acute lymphoblastic leukemia." (PMID 26848862, 2016). "One such derivative, PKC412 (midostaurin), has advanced into phase III clinical trials for the treatment of acute myeloid leukemia (AML) expressing the mutant tyrosine kinase receptor FLT3/CD135, itself a PKC412 target." (PMID 25699542, 2015). "We previously showed that MYB was a direct activator of FLT3 expression within the context of acute myeloid leukaemia." (PMID 26382271, 2015). "Lestaurtinib, midostaurin, sorafenib, and quizartinib were selected among the FLT3 inhibitor drugs that are currently used in clinics for the treatment of acute myeloid leukemia." (PMID 26625890, 2015). "To investigate Flt3 regulation in the context of uncommitted early progenitor cells, we applied a similar approach that we used previously in the context of acute myeloid leukaemia." (PMID 26382271, 2015). "FLT3-ITD and FLT3-TKD are the most frequent tyrosine kinase mutations in acute myeloid leukemia (AML), with the former associated with poor prognosis." (PMID 25826077, 2015). "In this study, we established quantitative fragment analysis of FLT3-ITD simultaneously measuring mutant allele burden and length, verified the analytical performance and evaluated the clinical significance in adult acute myeloid leukemia (AML) patients." (PMID 26832846, 2015). "In acute myeloid leukemia, the oncogenic Flt3 mutant Flt3-ITD activates STAT5 only on the ER25, 26, 27, as shown here for mutant Kit." (PMID 25493654, 2014). "AC220 (Quizartinib) is a second-generation Flt3 inhibitor developed to treat patients with acute myeloid leukaemia." (PMID 25336251, 2014). "When acute myeloid leukemia cells with constitutively active Flt3 mutants, such as Flt3-ITD and Flt3(D835Y), are treated with statins (HMG-CoA reductase inhibitors), this reduces Akt activation by blocking receptor trafficking towards the PM25." (PMID 25493654, 2014). "These efforts led to the discovery of a number of compounds that exhibited both high potency against FLT3-driven human acute myeloid leukemia (AML) MV4-11 cells and a considerable anti-angiogenic effect in transgenic-zebrafish-based assays." (PMID 25250310, 2014).
acute myeloid leukemia (continued). "FLT3 is the most frequently mutated kinase in acute myeloid leukemia (AML)." (PMID 24849514, 2014). "Internal tandem duplications in the juxtamembrane domain of Flt3 have been identified in patients with acute myeloid leukemia." (PMID 24739671, 2014). "The type III receptor tyrosine kinase fms-like tyrosine kinase 3 (FLT3) is expressed on both normal hematopoietic stem cells and acute myeloid leukemia (AML) cells and regulates their proliferation." (PMID 24040307, 2013). "High levels of WT FLT3-expression have been observed in various hematological malignancies including the majority of acute myelogenous leukemias (AMLs) and B-cell acute lymphoblastic leukemias (ALLs)." (PMID 23936658, 2013). "It inhibits mutant and wild-type FLT3 in vivo at 0.1 and 0.5 μM, respectively, and has shown favorable activity and tolerability in phase I and II trials in acute myeloid leukemia, with QT prolongation as the dose-limiting toxicity." (PMID 23967177, 2013). "For acute myeloid leukemia the panel is composed of FLT3ITD/FLT3-TKD, NPM1, C-KIT, PTPN11 and CEBPA." (PMID 23863689, 2013). "FLT3 and nucleophosmin (NPM1) mutations are playing important roles in individualizing treatment decisions on acute myeloid leukemia." (PMID 24252729, 2013). "Tandutinib, known as a small-molecule inhibitor of FLT3, is mainly used for acute myelogenous leukemia (AML) and is currently in phase II clinical trials." (PMID 23525656, 2013). "Fms-like tyrosine kinase 3 (FLT3) is expressed and activated in many human leukemias, including a significant percentage of acute myeloid leukemia (AML), and infant/childhood acute lymphoblastic leukemia (ALL)." (PMID 22970245, 2012). "CEP-701 known as Lestaurtinib is an Fms-like tyrosine kinase 3 (FLT3) inhibitor in current use on acute myeloid leukemia clinical trials and a JAK2 kinase inhibitor which suppresses phosphorylation induced by JAK2 tyrosine kinase." (PMID 22400031, 2012). "Clinical responses achieved with FLT3 kinase inhibitors in acute myeloid leukemia (AML) are typically transient and partial." (PMID 21980431, 2011). "In human acute leukemia, FLT3 is expressed on the surface of the leukemic cells in 70–90% acute myeloid leukemia (AML) patients and most B-acute lymphoblastic leukemia (B-ALL)." (PMID 21552520, 2011). "Data from different sources suggest a pathogenic role of FLT3 in acute myeloid leukemia (AML)." (PMID 19330068, 2008). "Indeed, our de novo somatic indel calling from TCGA RNA-seq increases the TCGA driver indel repertoire by ∼14%, especially in samples with purity less than 0.4, including actionable EGFR indels in lung adenocarcinoma and FLT3 in acute myeloid leukemia." (PMID 41781335, 2026). "Background/Objectives: Acute myeloid leukemia (AML) is a hematological malignancy frequently driven by mutations in the FLT3 gene, particularly internal tandem duplications (FLT3-ITD), which contribute to aberrant cell proliferation and resistance to tyrosine kinase inhibitors (FLT3i)." (PMID 42198431, 2026). "This case demonstrates that an isolated CNS relapse can occur in acute myeloid leukemia patients who are otherwise in complete hematological and molecular remission, and that targeted therapy, where applicable, as in our case against FLT3, can result in renewed remission." (PMID 41550394, 2026). "Finally, we found that OAS3 was observably related with some mutation types (CEBPA, FLT3 internal tandem duplication, NRAS, and EVI1 expression) in patients with acute myeloid leukemia (LAML)." (PMID 41700140, 2026). "FLT3 is a key oncogenic driver in acute myeloid leukemia (AML)." (PMID 41958931, 2026). "The presence of FMS-like tyrosine kinase 3 internal tandem duplication (FLT3-ITD) mutation, common in acute myeloid leukemia (AML) but rare in MPAL, introduces further uncertainty regarding optimal treatment strategies, particularly regarding the use and timing of FLT3 inhibitors." (PMID 42028519, 2026).
acute myeloid leukemia (continued). "Furthermore, when applied to inhibitor discovery against FLT3 for acute myeloid leukemia, AdaMBind successfully identified candidate compounds with potent inhibitory activity, as verified by preliminary experimental assays." (PMID 41807414, 2026). "Activating FLT3 lesions—primarily internal tandem duplications (ITD) and, less commonly, tyrosine kinase domain (TKD) point mutations—are among the most druggable targets in acute myeloid leukemia (AML), occurring in ∼30% of cases." (PMID 41347170, 2025). "Furthermore, Sorafenib displayed superior antitumor efficacy in FLT3-ITD acute myeloid leukemia patients, especially undergoing allogeneic hematopoietic stem-cell transplantation." (PMID 39706989, 2025). "For instance, HO-1 has emerged as a significant prognostic marker in acute myeloblastic leukemia (AML), particularly in cases involving the Fms-Like Tyrosine Kinase Receptor 3 (FLT3) gene Internal Tandem Duplication (ITD) mutation, which is associated with poor outcomes." (PMID 39287890, 2025). "Acute myeloid leukemia (AML) patients with the FMS‐related receptor tyrosine kinase 3 internal tandem duplication (FLT3/ITD) mutation have a poorer prognosis, and treatment with FLT3 tyrosine kinase inhibitors (TKIs) has been hindered by resistance mechanisms." (PMID 39395205, 2025). "Notably, MPI has been shown to potentiate therapeutic responses in acute myeloid leukemia, enhancing cellular sensitivity to both conventional cytarabine chemotherapy and targeted FLT3 inhibitors." (PMID 40853920, 2025). "Quizartinib, an FMS - like tyrosine kinase 3 (FLT3) inhibitor, specifically blocks FLT3 receptor tyrosine kinase activity, suppressing downstream signaling pathways and preventing FLT3-ITD-mutant acute myeloid leukemia cells from proliferating and surviving while inducing apoptosis." (PMID 40519935, 2025). "Furthermore, mRNA-sequencing provides insight on driving and co-occurring lesions (discussed later), specifically those amenable to targeted therapies with demonstrated efficacy in other diseases (e.g. FLT3 in Acute Myeloid Leukemia)." (PMID 40247105, 2025). "Furthermore, Tunicamycin C has been demonstrated to arrest under glycosylated FLT3-ITD in the endoplasmic reticulum and promote STAT5 activation in FLT3-ITD mutant cells in acute myeloid leukaemia." (PMID 40699738, 2025). "In summary, our hypothesis posited a scenario of overall reduced DNA methylation coupled with the overexpression of misregulation in cancer pathway-related genes in FLT3 mutant acute myeloid leukemia." (PMID 38944027, 2025). "Although FLT3 mutations are not as common in JMML as in acute myeloid leukemia, they can occur and can be a target for maintenance therapy." (PMID 40530013, 2025). "Consequently, FLT3 activation represents a viable molecular target for acute myeloid leukemia treatment." (PMID 39683494, 2024). "Acute myeloid leukemia (AML) arises from the clonal expansion of aberrant hematopoietic stem cells, for which early events like CH-associated mutations together with later events like FLT3-ITD, NRAS or NPM1 mutations initiate the disease." (PMID 37880479, 2024). "In FLT3-ITD-positive acute myeloid leukemia, suppressing CHK1 activity reduces cell proliferation." (PMID 39048945, 2024). "This review primarily focuses on PTMs of FLT3 in acute myeloid leukemia." (PMID 38915288, 2024). "Additionally, a comprehensive cell screening platformrevealed acute myeloid leukemia cells with FLT3 internal tandem duplicationmutations are particularly sensitive to these inhibitors." (PMID 39591507, 2024). "Notably, the knockdown of circ0060467 has been shown to suppress proliferation and enhance FLT3-ITD acute myeloid leukemia cell differentiation by promoting FLT3 kinase translational efficiency." (PMID 38244593, 2024).